KDR (kinase insert domain receptor)
Diseases named in the same sentence as KDR in open-access papers (continued):
Sharing a sentence is not in itself a finding about the gene and the disease.
Stroke (64 papers, 2008 to 2026). Sudden impairment of blood flow to a part of the brain due to occlusion or rupture of an artery to the brain. "In contrast, only reductions in D30 CD133 + KDR + (r: − 0.397; p: 0.006) and CD34 + CD133 + KDR + (r: − 0.399; p: 0.005) cell numbers were correlated with stroke severity on D90." (PMID 38071215, 2023). "Diminished total antioxidant capacity and CD34 + KDR + and CD133 + KDR + counts in early phases of stroke were associated with disease severity and worse functional outcome at day 90 post-stroke." (PMID 38071215, 2023). "Association of NIHSS, mRS and BI scores at D90 to the numbers of circulating EPC subtypes pinpointed substantial correlations between decreased BL numbers of CD34 + KDR + and stroke severity on D90 (NIHSS: r: − 0.281; p: 0.043; mRS: − 0.343; p: 0.01)." (PMID 38071215, 2023). "Scrutiny of the correlation between circulating EPC subtypes and the levels of key elements capable of affecting their counts showed that only BL level of angiogenic factor PDGF-BB (r: 0.334; p: 0.043) increased CD34 + KDR + numbers on D90 after stroke." (PMID 38071215, 2023). "Endothelial progenitor cells (EPCs), expressing markers for stemness (CD34), immaturity (CD133) and endothelial maturity (KDR), may determine the extent of post-stroke vascular repair." (PMID 38071215, 2023). "Close correlation between baseline CD34 + KDR + and CD133 + KDR + counts and the outcome of stroke proposes these particular EPC subtypes as potential prognostic markers for ischaemic stroke." (PMID 38071215, 2023). "The research group confirmed that catalpol promotes angiogenesis and maturation after stroke, which is closely related to the upregulation of VEGF/KDR protein expression and the regulation of Jak2/Stat3 signal." (PMID 33505489, 2021). "However, recent observation of a close correlation between baseline CD34+KDR+ and CD133+KDR+ counts and the outcome of stroke supports the idea that these particular EPC subtypes can be used as potential prognostic markers for ischaemic stroke." (PMID 38247804, 2024).
thyroid cancer (61 papers, 2010 to 2025). "Finally, cell growth assay showed that the loss of cell proliferation ability in KDR sgRNA_2 cells was remarkably recovered in KDR gene rescued cells, indicating the tremendous anti‐thyroid cancer potential of KDR targeting." (PMID 35313079, 2022). "In contrast, the KDR gene expression was 5.24 ± 0.64 in thyroid cancers and 4.28 ± 0.024 in other cancers (1.94‐fold, P = 0.001), respectively." (PMID 35313079, 2022). "We further used KDR sgRNA_2 virus‐infected SW579 cells to investigate the potential biological impact of KDR in advanced thyroid cancers." (PMID 35313079, 2022). "Even though with the strong evidence showed in this study, there is still KDR targeted anti‐cancer drug approved by the in advanced thyroid cancer." (PMID 35313079, 2022). "Our study demonstrated that the KDR gene in thyroid cancer cells was almost completely knocked out, accompanied by the inhibition of cell growth suppression and the loss of invasion ability." (PMID 35313079, 2022). "To confirm the predominant KDR expression in thyroid cancers, we further analyzed KDR gene expression in both thyroid and other types of cancers through the TCGA database." (PMID 35313079, 2022). "Five hundred thirteen thyroid cancer tissues had significantly higher KDR gene expression intensity (10.63.74 ± 0.049) than 7702 other types of cancers (9.06 ± 0.018) (P < 0.001)." (PMID 35313079, 2022). "The current study used CRISPR/Cas9 engineering in a lentivirus delivery system to target the KDR DNA locus of human chromosome 4 (q12) on SW579 thyroid cancer." (PMID 35313079, 2022). "To validate the potential of KDR as a therapeutic target for thyroid cancers, we used the KDR RTK inhibitor sunitinib." (PMID 35313079, 2022). "CRISPR‐mediated KDR gene editing would enable the investigation of the biological impact of KDR expression on cell survival and cancer metastasis in thyroid cancers." (PMID 35313079, 2022). "In tissue microarray, the immunohistochemistry assay showed weak KDR protein expression, whereas thyroid cancer cells exhibited strong but non‐homogeneous KDR expression (arrowhead)." (PMID 35313079, 2022). "The present study shows that VEGFR2/KDR overexpression in advanced thyroid cancer maintains cancer malignancy and cell survival." (PMID 35313079, 2022). "The KDR-KO significantly reduced SW579 sprouts formation in vitro, confirming that including selective targeting of KDR to anti-cancer therapy to suppress the VEGF/VEGFR axis in patients with clinical advanced thyroid cancers might increase its efficacy." (PMID 36497228, 2022). "Furthermore, it is highly possible that targeting KDR would provide effective anti‐cancer therapy for squamous thyroid cancer, ultimately improving the disease survival rate of advanced thyroid cancer patients in the clinic." (PMID 35313079, 2022). "Thus, developing effective and selective inhibitors or combinational drug treatments targeting KDR in advanced thyroid cancer patients remains unexplored." (PMID 35313079, 2022). "Furthermore, we performed the gene rescue assay to confirm these bio‐functional alternation findings in KDR gene edited thyroid cancer cells." (PMID 35313079, 2022). "Next, we investigated whether KDR protein expression is highly expressed in clinical thyroid cancer tissues through The Human Protein Atlas." (PMID 35313079, 2022). "The findings showed a positive association between the expression of KDR and ULBP1 and HS6ST2 expression in 11 different types of cancer (in particular, kidney renal papillary cell carcinoma, sarcoma, skin cutaneous melanoma, thyroid carcinoma, and uterine corpus endometrial carcinoma)." (PMID 37932473, 2023). "Thus, selective targeting of VEGFR2/KDR signaling may be a potential strategy for advanced thyroid cancer treatment." (PMID 35313079, 2022). "However, the expression evaluation and the biological function of KDR in advanced thyroid cancer remain unclear." (PMID 35313079, 2022).
thyroid cancer (continued). "This inhibitory effect suggested that KDR mediates VEGF signaling and plays a critical role in thyroid cancer development in cancer cell growth and cancer metastasis." (PMID 35313079, 2022). "Here, we show that both VEGFC and VEGFR2/KDR are overexpressed in thyroid cancers, indicating that VEGF/VEGFR signaling plays a carcinogenic role in thyroid cancer development." (PMID 35313079, 2022). "Next, we performed the matrigel‐coated transwell assays to examine the impact of the absence of KDR on advanced thyroid cancer." (PMID 35313079, 2022). "A novel PTTG-mediated proliferative pathway may be critical in thyroid cancer growth and progression by upregulating VEGF and kinase insert domain receptor (KDR) expression; however, in contrast, it has been shown that VEGF is not correlated with MVD." (PMID 25834571, 2015). "In this study, we evaluated the anti‐cancer effects of sunitinib on SW579 cells to reveal whether or not KDR targeting could potentially be used as cancer therapy for advanced thyroid cancer patients." (PMID 35313079, 2022).
endothelial dysfunction (59 papers, 2009 to 2026). In vascular diseases, endothelial dysfunction is a systemic pathological state of the endothelium (the inner lining of blood vessels) and can be broadly defined as an imbalance between vasodilating and vasoconstricting substances produced by (or acting on) the endothelium. "Indeed, recombinant human HtrA4 can cleave the main surface receptor for vascular endothelial growth factor (VEGF)-A which is also known as kinase insert domain receptor (KDR), causing an inhibition of VEGF-A action and endothelial dysfunction." (PMID 34639128, 2021). "Therefore, the predicted binding of STAT1 and KDR may be related to KDR overexpression and endothelial dysfunction in CH, which needs further investigation." (PMID 38650036, 2024). "However, the role of EPCs CD45+CD34+KDR+ within endothelial dysfunction may be still under debate, since converse results have been obtained, probably due to differences in the design to explore this target." (PMID 36831250, 2023). "KDR codes for a VEGF receptor that is significantly decreased in PE and may contribute to the endothelial dysfunction observed in PE." (PMID 26010865, 2015). "Besides increasing exercise capacity in these patients, physical exercise also improves endothelial dysfunction and decreases certain inflammatory mediators, such as C-reactive protein, superoxide dismutase, 8-isoprostane, and CD34/KDR+ endothelial progenitor cell count." (PMID 24616817, 2014).
atherosclerosis (54 papers, 2009 to 2026). A disease characterized by the build-up of fatty material and calcium deposition in the arterial wall resulting in partial or complete occlusion of the arterial lumen. "Consistently, CD34+KDR+ cell count correlates with cumulative indexes of CV risk and is an independent predictor of atherosclerosis progression and CV events." (PMID 35923624, 2022). "ATR could act on the KDR gene, which is one of the key molecules related to angiogenesis and a strong risk factor for atherosclerosis, while CR can act on its ligand VEGFA." (PMID 32802132, 2020). "Indeed, CD133+/CD34−/kinase insert domain receptor+ cells in peripheral blood are often taken as a sign of unstable atherosclerosis." (PMID 35155684, 2022). "Further insight into the role of progenitor cells in atherosclerosis in humans has focused on the use of cells that label both with CD34+, a marker of hematopoetic stem cells, and with KDR+, a marker of endothelial cell fate." (PMID 20407620, 2009).
angiosarcoma (50 papers, 2009 to 2025). A malignant tumor arising from the endothelial cells of the blood vessels. "The Angiosarcoma Project reported KDR mutations at a rate significantly higher than expected by chance, with a 25.5% recurrence rate - notably, 89% of KDR missense mutations observed in primary breast AS samples." (PMID 40666093, 2025). "Conversely, seven out of eight patients presenting KDR mutations were diagnosed with breast AS in the Angiosarcoma Project." (PMID 38137511, 2023). "In angiosarcomas, the most frequently mutated genes in all three cohorts were KDR, PIK3CA, and NF1, followed by KMT2D, NRAS, and PLCG1, which were among the top 10 genes in two of the three cohorts." (PMID 37568749, 2023). "Anti‐VEGF agents seem a coherent approach given the vascular phenotype of angiosarcoma and the identification of KDR (a gene encoding for VEGFR2) activating mutations in up to 26% of cases." (PMID 35971325, 2022). "The assessment of activity of anti-angiogenic agents in advanced angiosarcoma makes sense, since the phenotype of this sarcoma and the frequent occurrence of KDR mutations, involving in the angiogenic signaling pathways." (PMID 33330082, 2020). "Nevertheless, activating mutations of KDR (D717V and A1056T) have been discovered in angiosarcomas and have been verified in vitro." (PMID 31470906, 2019). "Point mutations in the KDR (VEGFR2) gene have been identified in a subset of primary and secondary angiosarcoma tumors from the breast and chest wall." (PMID 25374893, 2013). "Previous studies on the genomic landscape of angiosarcoma have described recurrent somatic mutations of angiogenic signaling pathway genes, including KDR, PTPRB, and PLCG114–18, as well as genes involved in oncogenic signaling pathways such as MAPK, PIK3CA/AKT/mTOR, and TP5319,20." (PMID 37106027, 2023). "Conversely, the addition of bevacizumab or pazopanib to weekly paclitaxel failed to improve outcomes, suggesting that combinations involving anti‐VEGF agents should probably be further explored in more selected angiosarcoma subtypes (e.g., angiosarcoma with KDR mutations)." (PMID 35971325, 2022). "Mutations in KDR that result in constitutive activation of the Vascular Endothelial Growth Factor Receptor 2 (VEGFR2) receptor leading to induction of angiogenesis signaling have been reported previously for other angiosarcoma tumors." (PMID 28056866, 2017). "Mutations in KDR have been reported previously in angiosarcomas." (PMID 28056866, 2017). "Moreover genomic analyses of the mutational status of the VEGFR (KDR) gene in angiosarcoma patients identified some mutations which correlated with increased sensitivity to VEGFR tyrosine kinase inhibitors (TKI) therapy." (PMID 22072937, 2011). "Prior studies have found that KDR, which encodes for a VEGFR2 receptor, is another frequently mutated gene in angiosarcoma." (PMID 41301029, 2025). "Among the genes historically linked to hemangiosarcoma, alterations in CDKN2A/B, KDR, MYC, and KIT were prominently identified in our study, underscoring their potential roles in the pathogenesis of this cancer in dogs." (PMID 39872607, 2024). "The detection of KDR gains is particularly intriguing, given its documented involvement in human angiosarcoma, suggesting a possible conserved oncogenic pathway between species." (PMID 39872607, 2024). "In our exploration of the genetic landscape of canine hemangiosarcoma, we focused on identifying copy number alterations (CNAs) within genes previously associated with the disease, including CDKN2A/B, VEGFA, KDR, SKI, MYC, and KIT." (PMID 39872607, 2024). "In HUVECs and mice, the drug suppresses vascular endothelial growth factor (VEGF)-induced kinase insert domain receptor (KDR) autophosphorylation and angiosarcoma development." (PMID 35408561, 2022).
angiosarcoma (continued). "Comparison of somatic copy number aberration profiles in human angiosarcoma and canine hemangiosarcoma identified recurrent copy number gains in KDR (31% in human, 22% in canine) and KIT (17% in both)." (PMID 32571313, 2020). "Genetic analysis of angiosarcomas uncovered mutations in genes such as Myc, FLT4, KDR, PLCγ and PTPRB9,10, and emerging evidence also implicates miRNAs in angiosarcoma pathogenesis." (PMID 31004117, 2019). "Considering that KDR gene amplification, KDR gene mutation and strong KDR (VEGFR2) expression in angiosarcoma have been previously reported, apatinib was given after the patient provided written informed consent." (PMID 29855279, 2018). "Focal MYC amplifications were identified in 8 (24%) angiosarcomas, VEGFR2 (KDR) amplifications in 4 (12%) tumors." (PMID 26440310, 2015). "Furthermore, our CNA analysis identified significant genomic regions linked to hemangiosarcoma pathogenesis, such as alterations in CDKN2A/B, VEGFA, KDR, MYC, and KIT." (PMID 39872607, 2024). "Our case may represent a subset of highly apatinib-responsive angiosarcomas characterized by KDR amplification." (PMID 29855279, 2018). "Herein, we report a patient with advanced angiosarcoma, who received apatinib at a daily dose of 250 to 725 mg, resulting in a partial response for three months, which may be related to Kinase Insert Domain Receptor (KDR) gene amplification." (PMID 29855279, 2018). "We also found KDR-ATRX to be mutually exclusive, which may indicate distinct biologies in angiosarcoma subclasses: angiogenesis dysfunction (KDR) and chromatin/telomere dysfunction (ATRX)." (PMID 41301029, 2025). "This heterogeneity in clinical behaviour might be related to the high genetic variability described in angiosarcomas, with several genes abnormalities identified in B-AS patients such as CIC, PLCG1, KDR and MYC." (PMID 32616718, 2020).
ischemia (49 papers, 2009 to 2025). A hypoperfusion of the BLOOD through an organ or tissue caused by a PATHOLOGIC CONSTRICTION or obstruction of its BLOOD VESSELS, or an absence of BLOOD CIRCULATION. "It has been proved that CD133+/KDR+ cells can differentiate into endothelial cells in vitro and in vivo, contributing to the re-endothelialization of the left heart, and promoting endothelial regeneration at the site of ischemia and vascular injury." (PMID 31847901, 2019). "The increase in the levels of both CD133+ cells and CD133+KDR+ cells in MI patients suggests that these cells are influenced by similar regulatory mechanisms and that these EPC subtypes are particularly important in the early phase of acute ischemia." (PMID 31428150, 2019).
sarcoma (47 papers, 2011 to 2025). A usually aggressive malignant neoplasm of the soft tissue or bone. "The expression levels of sunitinib targeted-kinases were measured by transcriptome sequencing for PDGFRA/B, KIT, RET, FLT1(VEGFR1), KDR (VEGFR2), and FLT4(VEGFR3) for patient cohort with EMC and other sarcoma histologies." (PMID 28423517, 2017).
breast tumor (46 papers, 1999 to 2025). "For example, PIK3CA and KDR mutations are predominantly found in AS tumors of the breast (7/7 and 9/11 samples with mutations in these genes, respectively, were from breast tissue)." (PMID 34296746, 2021).
triple-negative breast carcinoma (44 papers, 2012 to 2026). An invasive breast carcinoma which is negative for expression of estrogen receptor (ER), progesterone receptor (PR), and human epidermal growth factor receptor 2 (HER2). "KDR expression has been identified as an independent predictor of a complete response to neoadjuvant chemotherapy in triple-negative breast cancer patients, and rs2305948 in KDR also tended to be associated with the treatment response." (PMID 37120792, 2023). "The interaction between ANLN and KDR could act as ANLN and KDR jointly as a prognostic in cancer survival, which could be applied to control triple negative breast cancer." (PMID 32560530, 2020). "Therefore, an alternative approach, inhibition of VEGFR-2/KDR, is worthy of investigation for treatment of triple-negative breast cancer." (PMID 29370209, 2018). "Our results suggest a novel strategy for triple negative breast cancer control by concomitantly modulating ANLN and KDR gene expression while administrating Tamoxifen to triple negative patients." (PMID 31636652, 2019). "KDR and ANLN were positively correlated at the transcriptional level when ANLN gene expression was perturbed in triple negative breast cancer cell lines SUM159PT and MDAMB231." (PMID 31636652, 2019). "In summary, TTAC-0001, a novel fully human monoclonal antibody against VEGFR-2/KDR, was shown to have anti-angiogenic effects and good anti-tumor efficacy for inhibition of tumor growth and neovascularization in a mouse orthotopic triple-negative breast cancer model." (PMID 29370209, 2018).